EGFR (epidermal growth factor receptor)
Diseases named in the same sentence as EGFR in open-access papers (continued):
Sharing a sentence is not in itself a finding about the gene and the disease.
cancer (continued). "By performing a proteome-wide profiling of GEO cell lines, we mapped a subset of proteins relevant for EGFR signaling including a subset of proteins previously reported to be involved in mechanisms of cancer resistance." (PMID 31557914, 2019). "All the cancer cell lines used in the study are known to overexpress wt-EGFR with a high basal level of phosphorylation, but their corresponding cancers are intrinsically resistant to TKIs in clinic." (PMID 31121829, 2019). "After day seven, cancer spheroids maintained their size and overexpression of phosphor-epidermal growth factor receptor (p-EGFR)." (PMID 31614722, 2019). "The HER2/c-erbB-2, EGFR protein positive expression rate in cancer tissue and normal gastric tissue were compared." (PMID 33817143, 2019). "Another potential target is the MMP family of enzymes that governs both cancer cell invasiveness and transactivation of EGFR." (PMID 30841571, 2019). "Our results showed that PanDrugs is able to establish an a priori stratification of cancer patients treated with Epidermal Growth Factor Receptor (EGFR) inhibitors." (PMID 31540260, 2019). "To elucidate the connections among EGFR dynamics, PM compartmentalization, and invasiveness of cancer cells, we have performed the TReD assay on EGFRs in seven breast epithelial cell lines: MCF10A, MCF7, BT474, SKBR3, MDA-MB-468, MDA-MB-231, and BT549." (PMID 30833579, 2019). "For example, the chronic administration of EGFR inhibitors for cancer treatment is thought to lead to heart failure." (PMID 31534849, 2019). "The majority of EGFR overexpressing cancer patients are yet to benefit from current anti-EGFR therapeutics." (PMID 31508364, 2019). "Several clinical studies combining PD-1/PD-L1 pathway inhibitors with EGFR inhibitors in cancer patients are on-going." (PMID 31470510, 2019). "These facts indicate the need of glutamine as a source for bioenergetics and biosynthesis in EGFR-mutated NSCLCs, as glucose is mainly used to sustain PPP and consequently cancer cells proliferation." (PMID 31795465, 2019). "Several reports established the cooperativity of cMet and the epidermal growth factor receptor (EGFR) in various cancers, including NSCLC." (PMID 31040125, 2019). "Target-related side effects are still the major obstacle for cancer patients who are undergoing EGFR inhibition treatment." (PMID 30733972, 2019). "According to the Catalog Of Somatic Mutations In Cancer (COSMIC), 594 types of EGFR mutations have been reported, with 93% of mutations are present in the gene encoding tyrosine kinase domain (exons 18 to 21)." (PMID 31722672, 2019). "Small molecule EGFR inhibitors at targeting EGFR activity have improved the clinical outcomes of patients with many cancers." (PMID 35582586, 2019). "Pyk2 takes part in different carcinogenic signaling pathways to promote cancer progression, including epidermal growth factor receptor (EGFR) signaling pathway." (PMID 31368612, 2019). "The study cohort was very heterogeneous in terms of the types of EGFR inhibitors, platforms, and cancer cell lines." (PMID 30621238, 2019). "We propose a plausible mechanism of anti-cancer action by small degraders through the allosteric site of EGFR." (PMID 31374910, 2019). "The toxicity profile of lumretuzumab in combination with the EGFR-targeted therapies, cetuximab and erlotinib, was manageable, but it exerted only a minimal clinical benefit in various cancers." (PMID 30930695, 2019). "BTK-TKIs were more effective than EGFR-TKIs in decreasing cancer cell viability and significantly impaired cell proliferation and clonogenicity." (PMID 31200752, 2019). "Functional studies performed in cancer with HER2 overexpression have shown that HER2 binds to other receptors of the epidermal growth factor receptor (EGFR) family, thus resulting in dimerisation and phosphorylation of these, even in the absence of ligands." (PMID 31645889, 2019).
cancer (continued). "The observation that EGFR inhibition can limit the growth of EGFR positive cancers has led to the development of various EGFR inhibitors including monoclonal antibodies and small-molecule inhibitors." (PMID 31546749, 2019). "Receptor tyrosine kinases (RTKs), such as HER2 and/or EGFR are important therapeutic targets in multiple cancer cells." (PMID 31921382, 2019). "It is believed that this work would be giving a reference for developing anti-cancer drugs targeted EGFR-TK." (PMID 31530043, 2019). "XL147 and Dovitinib showed p-EGFR inhibition and induced the death of A549 cancer spheroids as well as single cells." (PMID 31614722, 2019). "Next, immunofluorescence imaging confirmed that small compounds specifically target EGFR in starved cancer cells." (PMID 31374910, 2019). "Epidermal growth factor receptor (EGFR) is overexpressed in various types of TNBC cells, and several EGFR-specific immunotherapies have been used to treat cancer patients." (PMID 31804974, 2019). "Our lab has previously provided critical insights into the role of Axl and the phenomenon of EGFR-Axl hetero-dimerisation in cancer cells, as well as the regulation of cell invasion by EGFR through utilising Axl signalling pathways." (PMID 31766614, 2019). "The use of KRAS mutation as a biomarker of exclusion for patients receiving anti-EGFR therapy, specifically cetuximab and panitumumab was a significant landmark in the advancement of cancer therapy." (PMID 31565185, 2019). "Our study uncovers new insights into SHOC2 biology and reveals inhibition of the SHOC2 phosphatase complex, alone and in combination with MEKi’s, as a therapeutic strategy to treat RAS- and EGFR-mutant cancers." (PMID 31182717, 2019). "In previous studies, we demonstrated that most EGFR-positive cancer cell lines are resistant to the EGFR antibody cetuximab and also to related tyrosine kinase inhibitors (TKIs)." (PMID 31546690, 2019). "Nanobodies that bind EGFR on cancer cells have been coupled in their monovalent format or as a trimer to anti-CD3 scFvs to ensure cross-linking and as such T cell activation 58,59." (PMID 31695800, 2019). "The activation of epidermal growth factor (EGF) receptor (EGFR) has been reported to translocate PKM2 into the nucleus in many human cancers." (PMID 31594538, 2019). "EGFR is already targeted in cancer; specifically monoclonal anti-EGFR antibodies (e.g., cetuximab) and EGFR kinase inhibitors (e.g., gefitinib) are FDA-approved to treat metastatic colorectal carcinoma." (PMID 30841571, 2019). "Other studies targeting EGFR expression on the surface of breast and lung cancer cells have also been reported." (PMID 30959799, 2019). "The second and third generation of EGFR-TKI therapy can induce a high response rate in patients with EGFR or Her2 dependent cancers, but high relapse rate becomes the major clinical problem." (PMID 31462678, 2019). "In DNA-based RNAi, a plasmid DNA is delivered to the brain, followed by the expression of a sequence-specific shRNA within the cancer cell that targets the EGFR mRNA." (PMID 31998120, 2019). "Another aspect of dysfunctional EGFR regulation in cancer is its altered subcellular distribution and protein turnover." (PMID 30890751, 2019). "Preliminary evidence on the role of activated MAPK pathway as mediators of EGFR promoted cancer tumorigenesis." (PMID 31747939, 2019). "Although cetuximab alone did not induce typical DDR, PC3 tumors displayed enhanced cell death, presumably due to the competent binding affinity of cetuximab to EGFR, a property that minimizes cancer survival." (PMID 31493351, 2019). "EGFR is also overexpressed in about one third of all human cancers, and EGFR-mediated activation of downstream signaling pathways is associated with poor patient outcomes." (PMID 30733972, 2019). "Accumulating evidence suggests that high expression and constitutive activation of EGFR are found in most cancers, including HCC." (PMID 30947731, 2019).
cancer (continued). "The gain of function in EGFR plays a critical role in driving the proliferation and survival of many types of cancer cells, via upregulating the AKT and MAPK pathways." (PMID 30910997, 2019). "Investigation of the mechanisms responsible for DDA selectivity for cancer cells reveals that DDA-induced upregulation of DR5 is enhanced in the context of EGFR overexpression." (PMID 31839995, 2019). "FAK inhibitors have been reported to fail to get the ideal anti‐cancer outcomes because of activation of EGFR signaling pathway." (PMID 31368612, 2019). "In fact, such NOX2-dependent mechanisms are likely responsible for increased EGFR cysteine oxidation in cancer cell lines under basal conditions, due to constitutive activation of EGFR ligands such as EREG." (PMID 30890751, 2019). "The amplification of EGFR also was found in other cancers, which contributed to the EGFR excessive activation." (PMID 32038722, 2019). "For example, treatment with the anti-epidermal growth factor receptor (EGFR) drugs cetuximab and panitumumab is ineffective in cancers that have mutations in RAS pathway genes." (PMID 31824558, 2019). "The FAMily with sequence similarity 83 (FAM83) members have recently been described as novel oncogenes in numerous human cancer specimens and shown to be involved in epidermal growth factor receptor (EGFR) signaling." (PMID 31083571, 2019). "Molecular analyses, such as EGFR mutational and ALK FISH tests, are required by patients with advanced NSCLC to guide the selection of anti-cancer drugs (EGFR tyrosine kinase or ALK inhibitors)." (PMID 30807604, 2019). "Epidermal growth factor receptor (EGFR) is a crucial target in cancer treatment as it can be found in many solid tumors including CRC." (PMID 30890933, 2019). "Here we tracked EGFRs and turned EGFR dynamics into a new type of biophysical biomarker to interrogate the relationships among advanced cancer malignancy, cortical actin organization, and EGFR dynamics." (PMID 31805710, 2019). "EGFR endocytic homeostasis is often dysregulated in various cancers, leading to irregular trafficking to intracellular organelles, specifically the nucleus." (PMID 30890751, 2019). "Dysregulated EGFR signaling is commonly found in cancers and conveys advanced aggressive malignancies: drug resistance, migration, invasion, and metastasis with poor prognosis." (PMID 31805710, 2019). "As an additional layer of complexity, an alternative, recently described mechanism by which cancer cells can be intrinsically or become secondarily resistant to EGFR-TKIs is “drug tolerance”." (PMID 31266248, 2019). "We assessed resistance to EGFR-TKIs by treating cancer cell lines with erlotinib, afatinib, or osimertinib, and serum collected from smokers within 30 min of smoking and that from a non-smoker as a control." (PMID 30818860, 2019). "The cancer lines chosen as representative of EGFR and HER2-overexpression, MDA-MB-468 and BT474, respectively, also exhibit MYC amplification." (PMID 31839995, 2019). "This study demonstrates for the first time that the PCNA-targeting peptide ATX-101 increases the anti-cancer effects of the EGFR/HER2/VEGFR inhibitor AEE788." (PMID 31921382, 2019). "Given its frequent expression in cancers, its powerful oncogenic function, and easy accessibility for targeting, EGFR remains an ideal therapeutic target for cancers." (PMID 31508364, 2019). "Herein, we demonstrate that some compounds behave as weak inhibitors of EGFR phosphorylation and show enhanced degradation of the receptor and cytoskeletal proteins, leading to cancer cell detachment-related death." (PMID 31374910, 2019).
cancer (continued). "VOPP1 (also known as Vesicular, Overexpressed in cancer, Prosurvival Protein 1 or EGFR-Co-amplified and Overexpressed Protein) expression is shown first in relation to EGFR expression, then to PCNA expression." (PMID 31857847, 2019). "One of the frequently used ligands to conjugate with AuNPs and employ further in thermal therapy is an anti-EGFR antibody (epidermal growth factor receptor), which is responsible for the cell transduction mechanisms in ordinary and cancer cells." (PMID 31450616, 2019). "The epidermal growth factor receptor (EGFR) signaling pathway is involved in cancer invasion and metastasis and regulation of gene expression, and is a prime target for the treatment of malignant cancers." (PMID 31216276, 2019). "This concentration difference on the cell surface is the basis for studies targeting cancer cells overexpressing EGFR." (PMID 31304563, 2019). "While both EGFR-NP and RGD-NP colocalized in regions with metastatic cancer cells, some metastatic regions were primarily targeted only by EGFR-NP or RGD-NP." (PMID 31356633, 2019). "Several histologic and cancer genome sequencing studies have revealed deregulation of EGFR and its downstream signaling pathways in GBM." (PMID 31215502, 2019). "Although these mAbs have shown anti-cancer effects, these anti-EGFR mAbs need further clinical validations." (PMID 31527477, 2019). "Epidermal growth factor receptor (EGFR) is a trans-membrane tyrosine kinase receptor of the ErbB-family, that plays an important role in the development of various types of cancers." (PMID 30630536, 2019). "Cancer cells are thought to promote migration through the phosphorylation of integrin β4, which is regulated by various RTKs, including EGFR." (PMID 31052260, 2019). "Radiation therapy “alone” seems to increase the cancer cells′ radioresistance through Akt gene activation, mediated by the concurrent activation of EGFR." (PMID 31801254, 2019). "This antibody was able to activate Vγ9Vδ2 T cells and triggered in vitro cytotoxicity against EGFR+ cancer cell lines." (PMID 31544819, 2019). "Some of these reports also indicated that following SCLC-transformation cancer cells became insensitive to EGFR-TKIs partly by downregulating the expression of EGFR protein and not by acquiring a secondary EGFR-mutation such as T790M." (PMID 31266248, 2019). "This phenomenon, where both IL-6 secretion and EGFR levels are often elevated, creates a perfect environment for cancer development and progression." (PMID 31470515, 2019). "Our research group also reported that EGFR signaling promoted inflammation and cancer stem-like cell activity in IBC, and the EGFR pathway is a promising therapeutic target for patients with triple-negative IBC (TN-IBC)." (PMID 31532791, 2019). "Several EGFR-specific monoclonal antibodies targeting the extracellular domain and small molecule TKIs targeting the tyrosine kinase domain of EGFR have been used as cancer therapies." (PMID 31804974, 2019). "As it can obviously influence the proliferation of human cancer cells, and even result in the apoptosis of human cancer cells, the EGFR has become a very luminous target for various antitumor candidates." (PMID 30769844, 2019). "The modified vaults bound specifically to cancer cells either directly (EGF modified vaults) or as mediated by a monoclonal antibody (anti-EGFR) bound to recombinant vaults containing the Z domain." (PMID 31261673, 2019). "Other reports have shown that CEMIP can suppress apoptosis via epidermal growth factor receptor (EGFR) signaling as well as by enhancing glycogen breakdown to promote cancer cell survival." (PMID 31303964, 2019). "EGFR signaling is a common pathway during carcinogenesis, and is frequently amplified in several cancers." (PMID 30487162, 2019). "The most frequently altered pathway in GBM and cancer in general involves both tyrosine kinase receptors (RTKs) and serine/threonine kinases such as the epidermal growth factor receptor (EGFR)." (PMID 30978987, 2019).
cancer (continued). "To evaluate this idea, we ectopically expressed the wild-type and S463D mutant of TFEB in three human cancer cell lines to modulate lysosomal acidification/activation and treated the cells with EGFR inhibitors under hypoxia." (PMID 31717697, 2019). "Due to the fact that cancer cells resistant to treatment often display overexpression of growth factor receptors, we checked the level of EGFR and MET in generated cell lines." (PMID 31877948, 2019). "The prevalence of EGFR as an oncogenic driver across many prominent types of cancers including GBM renders EGFR an appealing target for therapeutic intervention." (PMID 31488827, 2019). "Binding of EGFR by the nanobody induced DR clustering at the cancer cell membrane, thereby sensitizing these cells to TRAIL and downstream caspase-mediated apoptosis." (PMID 31695800, 2019). "An obvious question raised by this discrepancy between suitable cancer types of TKIs vs. mAbs is: Is inhibition of the kinase activity of EGFR primarily accountable for the efficacy of anti-EGFR mAbs?" (PMID 31508364, 2019). "In this study, a series of chalcone derivatives was screened by in vitro cytotoxicity against the wild type (A431 and A549) and mutant EGFR (H1975 and H1650) cancer cell lines, and, subsequently, tested for EGFR-tyrosine kinase (TK) inhibition." (PMID 30897725, 2019). "Treatment with curcumin, as an adjuvant intervention to a chemotherapeutic regimen named FOLOX, resulted in cancer cell apoptosis through downregulating the epidermal growth factor receptor (EGFR) and IGF-1R expression." (PMID 30987250, 2019). "EGFR is a group of transmembrane receptor tyrosine kinases (RTKs) that are normally deregulated in various cancers." (PMID 31877856, 2019). "The derivative with the presence of an amine group has shown higher potency against proliferation of cancer cells through the inhibition of EGFR." (PMID 30781671, 2019). "The epidermal growth factor receptor (EGFR) signaling is commonly up-regulated in cancer, constituting an important pathway that regulates cell growth, survival, proliferation and differentiation." (PMID 30959964, 2019). "Targeting of DRs on cancer cells using TRAIL is an interesting strategy that was shown to act in concert with EGFR-targeting." (PMID 31695800, 2019). "We applied the cancer spheroid array to identify highly effective drugs targeting p-EGFR from among seventy drugs (including ten EGFR-targeting drugs as model drugs) by using a p-EGFR-overexpressing cell line (A549 cell line)." (PMID 31614722, 2019). "Recent reports showed that CEMIP can suppress apoptosis via EGFR signaling as well as by enhancing glycogen breakdown to promote cancer cell survival." (PMID 31303964, 2019). "The epidermal growth factor receptor (EGFR) is one of most potent oncogenes that are commonly altered in cancers." (PMID 31508364, 2019). "To further improve the drugs delivery system and pharmacokinetics profiles, we co-encapsulated the EGFR drugs and integrin αvβ3 inhibitors to achieve enhanced anti-cancer effects and reduced systemic toxicity." (PMID 31316001, 2019). "Raoof and her colleagues performed whole-genome CRISPR screening and identified FGFR3 as the top target facilitating the survival of mesenchymal EGFR mutant cancers." (PMID 31998131, 2019). "And the positive rates of EGFR in cancer and paired normal gastric tissues were 41.8% (28/67) and 5.9 (4/67), respectively with statistical difference (p<0.05)." (PMID 33817143, 2019). "Better understanding of Pyk2 downstream targets and interconnectivity between Pyk2 and carcinogenic EGFR signaling pathway will help finding more effective targets for clinical anti‐cancer combination therapies." (PMID 31368612, 2019). "SCD1 modulates the activity of EGFR/Akt/ERK signaling pathway to control cancer cell metabolism, proliferation and survival." (PMID 31019378, 2019). "In recent years, Pyk2 is found to be involved in epidermal growth factor receptor (EGFR) signaling pathway in cancer progression." (PMID 31368612, 2019).